IRS1 (insulin receptor substrate 1)
Diseases named in the same sentence as IRS1 in open-access papers (continued):
Sharing a sentence is not in itself a finding about the gene and the disease.
Insulin resistance (continued). "Additionally, 1-Deoxynojirimycin supplementation appeared to improve muscle insulin resistance by modulating the IRS-1/PI3K/AKT pathway in the skeletal muscle of db/db mice." (PMID 38799166, 2024). "However, when overnutrition persists owing to continuous exposure to HSD, CUL1 proteins accumulate in cells and eliminate IRS1 proteins, leading to insulin resistance." (PMID 38212312, 2024). "It reduces Irs1 protein levels, which can contribute to insulin resistance." (PMID 39519546, 2024). "Of note, semaglutide may also improve insulin resistance, triggering upregulation of phosphorylated IRS-1." (PMID 39728000, 2024). "In this context, the increased phosphorylation of the inhibitory sites of IRS1 might represent a factor further exacerbating the insulin resistance." (PMID 37298533, 2023). "Moreover, IL-6 increases the expression of the suppressors of cytokine signaling (SOCS) 1 and SOCS3, leading to the degradation of IRS-1 and the development of insulin resistance." (PMID 37876013, 2023). "It remains to be investigated whether teaghrelin is also able to prevent muscle atrophy by inhibiting GLUT4 translocation or IRS-1 signaling in insulin resistance-induced animal models." (PMID 36677745, 2023). "Overexpression of OGT in the liver influences the phosphorylation of insulin-responsive proteins, namely, Akt and insulin receptor substrate 1 (IRS-1), which inhibits the kinase activity of Akt and induces the serine phosphorylation of IRS1, thus resulting in insulin resistance and dyslipidemia." (PMID 36768465, 2023). "Conversely, during insulin resistance, IRS1 is inhibited and prevents downstream signaling." (PMID 37108445, 2023). "One potential mechanism that could elucidate the relationship between JNK1-mediated brain insulin resistance and cognitive decline involves the phosphorylation of the insulin receptor substrate 1 (IRS1) on Ser-307." (PMID 37762479, 2023). "ATM significantly secretes anti-inflammatory cytokines such as IL-10 that contribute to insulin resistance, impairs phosphorylation through insulin receptor substrate 1 (IRS1) and PI3K/AKT pathway related to IRS1, and reduces hepatocyte responsiveness to insulin." (PMID 37274349, 2023). "Additionally, hepatic insulin resistance, via impaired IRS1/2 sensitivity, will result in impaired glycogen storage, increased gluconeogenesis, and increased triglyceride accumulation in hepatocytes." (PMID 37842470, 2023). "Moreover, SOCS3 ubiquitinates IRS-1 to induce its degradation, leading IL-6 to induce insulin resistance." (PMID 37555019, 2023). "Researchers have measured the levels of IRS-1, PI3K p85a and GLUT-4 mRNA and corresponding proteins in this signalling pathway and found that activation of the IRS-1/PI3K/Glut-4 signalling pathway reduced insulin resistance and thus improved blood glucose levels." (PMID 37089923, 2023). "The mechanism of interaction between insulin resistance and hyperuricemia may be explained by the phosphorylation of insulin receptor substrate 1 and the increasing oxidase activity of xanthine and nicotinamide adenine dinucleotide phosphate." (PMID 37483942, 2023). "Insulin resistance induced by hyperglycemia and obesity also converges with inflammation and immune modulation in the insulin receptor substrate 1 (IRS-1)/mitogen-activated protein kinase (MAPK)/Akt/phosphatidylinositol-3 kinase (PI3K) and NF-κB/IL-1β/TNF-α/interferon-γ (IFN-γ) pathways." (PMID 37298118, 2023). "Decreased expression of the IRS1 gene in this study, could indicate insulin resistance in laying hens under physiological stress." (PMID 37560158, 2023).
Insulin resistance (continued). "However, when insulin resistance is induced, the signaling of IRS-1, an insulin receptor substrate, and AKT, which regulates glucose and lipid metabolism, is downregulated, thereby affecting the expression of downstream factors." (PMID 37754257, 2023). "By increasing insulin receptor phosphorylation, resveratrol may also enhance insulin signaling in animals with insulin resistance in their skeletal muscles and increased protein levels of IRS-1." (PMID 37241737, 2023). "These metabolites may alleviate insulin resistance in IR-HepG2 cells by regulating the expression levels of genes related to the IRS-1/PI3K/Akt signaling pathway." (PMID 38201125, 2023). "Importantly, mice with inactivation of TLR4 are protected against the development of insulin resistance, and show higher levels of adiponectin and IRS-1 gene expression." (PMID 38136564, 2023). "IL-1β decreases IRS-1 tyrosine phosphorylation and its gene expression, inhibiting the insulin signaling pathway required for glycemic control and contributing to the development of insulin resistance." (PMID 37372020, 2023). "All fermentation supernatants could alleviate the insulin resistance of IR-HepG2 cells by regulating the expression levels of genes related to the IRS-1/PI3K/Akt signaling pathway." (PMID 38201125, 2023). "Further, the lower hepatic expression of IRS‐1 and AMPK due to CAF may be associated with the presence of insulin resistance and hepatic lipid accumulation." (PMID 37970433, 2023). "Some reports suggested that serum uric acid per se might inhibit insulin receptor substrate 1 (IRS1) and Akt insulin signaling and induce insulin resistance." (PMID 36681819, 2023). "This might also help to explain the present observation of acute reduction in the myocellular inhibitory serine-1101 phosphorylation of IRS-1, generally known to mediate lipid-induced or chronic insulin resistance in human skeletal muscle." (PMID 36178534, 2023). "Furthermore, the phosphorylation of IRS‐1 at Ser307 attenuates insulin signaling and contributes to insulin resistance." (PMID 38107110, 2023). "Moreover, adipose tissue insulin resistance was characterized by an increased deleterious phosphorylation of IRS-1 on the serine residue, leading to insulin receptor (IR) signaling disruption." (PMID 38136564, 2023). "Similarly, the genetic polymorphisms in different genes such as CAMK2, IGF1, IRS1, GCKR, PPARG, GCK1, and KCTD1 are found associated with insulin resistance and T2DM." (PMID 37829557, 2023). "Furthermore, JNK1/2 contributes to insulin resistance through various mechanisms, such as phosphorylation of insulin receptor substrates (IRS)-1/2 and the stimulation of inflammation in metabolic processes." (PMID 37375718, 2023). "Insulin resistance is mediated by the IRS1/AKT signaling pathway and PPAR‐γ expression." (PMID 36333974, 2023). "Rare mutations of the insulin receptor gene and IRS1 protein lead to insulin resistance." (PMID 37560158, 2023). "Human placental growth hormone (hPGH) may involved in insulin resistance by increasing the expression of the p85-regulatory unit of PI3K, resulting in a marked reduction in IRS-1-associated PI3K activity." (PMID 36631877, 2023). "MA attenuates insulin resistance in skeletal muscle by activating the insulin receptor substrate-1/PI3K/Akt signaling pathway, and flavonoids derived from MA have been associated with improvements in type 2 diabetes through enhanced mitochondrial function in the muscle." (PMID 37674382, 2023). "In diabetes, IRS-1 phosphorylation has been established to be related to insulin signal transduction, hence galangin, and pinocembrin reinstate the sensitivity of insulin receptors and diminish insulin resistance." (PMID 36028892, 2022). "In the 3xTg-AD murine model, oxidative stress, after inducing initial activation of IRS-1, activates negative feedback mechanisms to turn off IRS-1 hyperactivity, causing brain insulin resistance." (PMID 35164216, 2022).
Insulin resistance (continued). "IRS-1 plays a key role in the regulation of insulin resistance and hepatic glucose metabolism." (PMID 35726320, 2022). "3,3′,4,5′-TMS ameliorated insulin resistance by enhancing the phosphorylation of glycogen synthase kinase 3 beta (GSK3β), inhibiting phosphorylation of insulin receptor substrate-1 (IRS-1), and activating phosphatidylinositol 3-kinase (PI3K)/protein kinase B (Akt) pathway in IR-HepG2 cells." (PMID 35678676, 2022). "The increase of IRS-1 phosphorylation at the residue ser307 (p-ser307-IRS-1) and decrease of p-ser473-Akt (p-Akt) are viewed as the insulin resistance markers, and our previous reports suggested dipeptidyl peptidase-4 (DPP-4) mediates insulin resistance, the crucial factor of metabolic syndrome." (PMID 35290413, 2022). "In hyperinsulinemia, such as in obesity or type 2 diabetes, the decreased serine-632 IRS-1 phosphorylation could exacerbate insulin resistance." (PMID 36547071, 2022). "Moreover, TNF-α, which is regulated by NF-κB, phosphorylates insulin receptor substrate-1 (IRS-1) leading to insulin resistance." (PMID 35846362, 2022). "Based on reported role of TAZ/IRS1 axis in statin‐induced insulin resistance in skeletal muscle, we hypothesized that TAZ/IRS1 axis might be involved in the beneficial effect of GGPP on insulin signalling." (PMID 35961942, 2022). "While our current findings do not provide a causal role of lactylation on skeletal muscle insulin resistance, it is significant to note that we also observed a lactate-induced increase in IRS-1 serine 636 phosphorylation which paralleled lactylation levels." (PMID 36111162, 2022). "In addition, FCX ameliorated insulin resistance by activating insulin receptor substrate 1 (IRS-1)/phosphatidylinositol 3-kinase (PI3K)/Akt and AMP-activated protein kinase (AMPK) signaling pathways in the liver and skeletal muscle of diabetic mice." (PMID 35684079, 2022). "Additionally, mutations or hyper-serine phosphorylation of the insulin receptor substrate-1 (IRS-1) protein and knockdown of the IRS-1 gene have resulted in a state of insulin resistance in human, mouse, and rodent models." (PMID 36499769, 2022). "The mechanism of leptin contribution to the development of insulin resistance may lie in its capacity to phosphorylate insulin receptor 1 substrate (IRS1) serine residues, which downregulates insulin signaling." (PMID 35682958, 2022). "ROS prevents IRS-1 from binding to the insulin receptor by activating IKKβ, which phosphorylates the IRS-1 SER site, thereby preventing the transmission of insulin signals and causing insulin resistance." (PMID 36699072, 2022). "CTPG effectively suppressed adipogenesis and lipid accumulation in 3T3-L1 adipocytes and ameliorated HFD-induced obesity and insulin resistance through activating AMPKα and IRS1/AKT/GLUT4 signaling pathway and regulating the composition and metabolic functions of gut microbiota." (PMID 36229811, 2022). "The activation of mTORC1 itself also can result in IRS-1 degradation leading to insulin resistance." (PMID 36309772, 2022). "Studies have reported a close relationship between insulin resistance (IR) and Aβ accumulation, where Aβ aggregation causes neuroinflammatory and c-Jun N-terminal kinase (JNK) activation of the serine residue insulin receptor substrate 1 (IRS-1)." (PMID 36501161, 2022). "The core protein of chronic hepatitis C virus (HCV) may impair insulin receptor substrate 1 (IRS-1) signaling and lead to insulin resistance." (PMID 35252271, 2022). "The down-regulation of the insulin receptor substrate 1 (IRS-1) pathway by TNF-α and a reduced activation of 5′-AMP activated protein kinase and AMPK (AMP-activated protein kinase) due to leptin resistance have been associated with insulin resistance." (PMID 35886175, 2022).
Insulin resistance (continued). "Since there are several possible mechanisms linking visceral fat accumulation with insulin resistance, we analyzed protein levels of IRS-1 and its inhibitory phosphorylation on Ser307, as well as levels of total and phosphorylated forms of Akt and Erk1/2 kinases in this tissue." (PMID 36012206, 2022). "In addition to promoting lipogenesis, activated mTORC1 can directly promote IRS1/2 degradation to induce insulin resistance." (PMID 36535507, 2022). "Mechanistically, MBCDs exposure-induced reactive oxygen species (ROS) overproduction activates the nuclear factor-κB (NF-κB) signaling pathway and MAPK cascade, thereby promoting phosphorylated insulin receptor substrate (IRS)-1 at Ser307 and inducing insulin resistance (IR)." (PMID 35842638, 2022). "The present study now extends these previous results in that both single lipid meals, but especially PAL already during the basal period, acutely increased membrane C18-containing DAG species, followed by nPKCθ translocation, serine1101-phosphorylation of IRS-1 and whole-body insulin resistance." (PMID 34704121, 2022). "It was reported that Q3G could reduce ROS production to prevent alcohol-induced cytotoxicity and improve insulin resistance by modulating IRS-1." (PMID 36501396, 2022). "Interestingly, higher level of phosphorylated insulin receptor (p-Ser-IRS1) has been shown to be a consistent change in insulin signaling and a marker of insulin resistance in AD brains." (PMID 35264925, 2022). "Consequently, HM-chromanone treatment under insulin-stimulated conditions significantly restored the activation of the sub-kinases of IRS-1 in cells with insulin resistance." (PMID 36145191, 2022). "It was believed to induce insulin resistance in adipose tissues by altering the normal insulin signaling pathway, stimulating adipocyte lipolysis, inhibiting serine phosphorylation of IRS-1 activity thereby decreasing glucose transporter ‘GLUT4’ synthesis and membrane translocation." (PMID 36434695, 2022). "Polymorphisms among genes (IRS1 and IRS2) have been found for insulin resistance." (PMID 35327342, 2022). "Different mechanisms might contribute to the dysregulation of the insulin signaling pathway, but many insulin resistance inducers activate IRS kinases targeting the IRS-1 protein." (PMID 35327570, 2022). "Furthermore, the insulin receptor substrates 1 and 2 (IRS1/2) present major targets for the induction of insulin resistance, for instance due to the accumulation of specific lipid metabolites." (PMID 35563150, 2022). "In the present study, KK-Ay mice showed obvious insulin resistance, increased serine phosphorylation levels of IRS-1 and tyrosine phosphorylation of GSK-3β, decreased activation of Akt and serine phosphorylation of GSK-3β, and protein expression of GLUT-2, in keeping with previous studies." (PMID 35153796, 2022). "Moreover, aerobic exercise attenuated insulin resistance by regulating the IRS-1/PI3K/AKT and the TNF-α/NF-κB signaling pathways." (PMID 36145106, 2022). "This may be because prolonged hyperinsulinemia activates the mTOR/S6 kinase pathway, which enhances the serine phosphorylation of IRS-1 and eventually induces insulin resistance in the hypothalamus." (PMID 36353235, 2022). "However, factors that lead to insulin resistance, such as TNFα, fatty acids, Cblb, and Crebbp, inhibit the IRS-1 down-regulation." (PMID 36353510, 2022). "Importantly, TRIM72 induces insulin resistance by mediating (as an E3 ligase) the degradation of the insulin receptor and insulin receptor substrate-1 (IRS1)." (PMID 36139694, 2022). "This kinase can phosphorylate IRS1 on serine residues to trigger insulin resistance." (PMID 35884769, 2022). "Furthermore, JNK can mediate insulin resistance via the phosphorylation of serine residues in IKKβ and insulin receptor substrate 1, which can further mediate insulin resistance via NF-κB." (PMID 36364178, 2022).
Insulin resistance (continued). "In addition to MAPKs, IL‐1β was shown to enhance the SOCS‐mediated degradation of IRS‐1/2 involving the IkappaB kinase beta (IKKβ)/NF‐κB pathway, promoting glucose intolerance and hepatic insulin resistance by this mechanism." (PMID 36101976, 2022). "In these studies, increased inflammatory modifications were observed in adipose tissue from obese rodents and humans, and enhanced secretion of pro-inflammatory cytokine tumor necrosis factor-α(TNF-α) was able to induce insulin resistance by inactivating insulin receptor substrate 1 (IRS-1)." (PMID 36012516, 2022). "Moreover, mTOR hyper-activation is also among the known feedback mechanisms promoting IRS1 inhibition and insulin resistance development in AD." (PMID 35628384, 2022). "IRS1 rs1801278 is a missense polymorphism that decreases the phosphorylation of IRS-1 in vitro, reducing the binding of p85 to IRS-1 and the activity of PI3K in different cell lines, and leading to insulin resistance." (PMID 35450164, 2022). "This inhibitory serine phosphorylation event leads to detachment of IRS1 from insulin receptor and consequently to impairments in insulin-mediated signaling that may also lead to insulin resistance." (PMID 36012331, 2022). "Palmitate treatment, a known factor causing insulin resistance, impairs the formation of the signal hubs of IRS1 condensates, which might contribute to the development of insulin resistance." (PMID 35790738, 2022). "The hypertrophic adipocytes secrete pro-inflammatory cytokines such as tumor necrosis factor-α (TNF-α), interleukin 6 (IL-6), interleukin 8 (IL-8), and monocyte chemoattractant protein 1 (MCP-1) which, through the phosphorylation of insulin receptor substrate-1 (IRS-1), cause insulin resistance." (PMID 35406070, 2022). "For example, Irs1 phosphorylation at S302, S307, S522, and S636/639 have been linked to insulin resistance, but not all hormones that phosphorylate those Irs sites induce insulin resistance, including FGF21." (PMID 36169399, 2022). "Therefore, an increase in phosphorylation of IRS1 on serine residues leads to insulin resistance and a decrease in Akt (a downstream molecule in the insulin signaling pathway) phosphorylation." (PMID 36143409, 2022). "Additionally, recent data showed that δ-valerobetaine also protected ECs against PA-induced insulin resistance (IR) by limiting the inhibitory phosphorylation of IRS1 and restoring phosphorylated Akt expression levels." (PMID 36232386, 2022). "Additionally, HPE reduced the markers of insulin resistance—insulin receptor substrate-1 and vimentin in the renal tubular region." (PMID 35885378, 2022). "The IRS1G972R mutation that causes human insulin resistance does not affect the formation of IRS1 condensates but decreases their fluidity in concomitance with impaired recruitment of p85 into the condensates." (PMID 35790738, 2022). "Akin to the skeletal muscle that accounts for 70%-80% of insulin-stimulated glucose disposal, inhibition of the IRS-1 ubiquitin pathway may also engage in alleviating insulin resistance." (PMID 36045953, 2022). "Thus, GSK3β-MG53-IR/IRS1 form a vicious cycle that exacerbates insulin resistance and glucose intolerance." (PMID 36337049, 2022). "In addition, IRS-1 expression has been known to be reduced in diabetic patients, and its depletion in mice resulted in insulin resistance and T2DM." (PMID 35328400, 2022). "Additionally, an upregulated expression of the pro-inflammatory gene Angptl4, which is supposed to increase insulin resistance, was observed; on the other hand, Irs1, a gene that improves insulin sensitivity, was downregulated." (PMID 36299624, 2022). "Overnutrition augments mTORC1 signaling, which in turn may generate insulin resistance via mTORC1/S6K-mediated IRS1 serine phosphorylation as well as the degradation of its total protein levels, attenuating the insulin signaling pathway." (PMID 35428325, 2022).